SCFD2 (sec1 family domain containing 2)
Description:
May be involved in protein transport.
Synonyms: STXBP1L1; FLJ39514
Tractability: PROTAC: ubiquitination databases record sites on it; its protein half-life has been measured.
Gene: Protein-coding gene on chromosome 4 (52,872,982 to 53,366,072, reverse strand). Ensembl gene ENSG00000184178.
Subcellular location (Human Protein Atlas): Nucleoplasm
Gene Ontology:
Biological process: vesicle-mediated transport
Genetic constraint (gnomAD): Loss-of-function variants: 51 observed, 54.5 expected, observed/expected ratio (o/e) 0.94, 90% interval 0.75 to 1.18. The upper end of that interval is the gene's LOEUF score, 1.18, which puts it in group 5 of 6, group 1 being the genes least tolerant of losing a copy. Missense variants: 733 observed, 814.79 expected, observed/expected ratio (o/e) 0.9, 90% interval 0.85 to 0.96. Synonymous variants: 296 observed, 327.5 expected, observed/expected ratio (o/e) 0.9, 90% interval 0.82 to 1.
Homologues: Orthologues: chimpanzee SCFD2 (99% identical), macaque SCFD2 (96% identical), pig SCFD2 (90% identical), dog SCFD2 (89% identical), guinea pig SCFD2 (87% identical), rat Scfd2 (85% identical), mouse Scfd2 (83% identical), rabbit SCFD2 (83% identical), tropical clawed frog scfd2 (60% identical), zebrafish scfd2 (56% identical), Caenorhabditis elegans uncp-18 (12% identical), zebrafish si:ch73-249k16.4 (12% identical). Paralogues in human: STXBP2 (16% identical), SCFD1 (15% identical), STXBP3 (14% identical), VPS33A (11% identical), VPS33B (11% identical), VPS45 (10% identical).
Diseases named in the same sentence as SCFD2 in open-access papers:
SCFD2 is named in the same sentence as 19 diseases in open-access papers, as found by Europe PMC text mining. Sharing a sentence is not in itself a finding about the gene and the disease. The quoted sentences say what the papers report.
breast carcinoma (4 papers, 2022 to 2024). "The paraspeckle component 1 (PSPC1)-Sec1 family domain containing 2 (SCFD2)-DDIAS axis is highly expressed in tamoxifen-resistant breast cancer and is a potential diagnostic and therapeutic target for estrogen receptor (ER)-positive breast cancer." (PMID 37121974, 2023). "In ERα‐positive breast cancer, PSF associates with the pre‐mRNAs of oncogenic genes, such as ERα (ESR1) and Sec1 family domain containing 2 (SCFD2), to sustain the mRNA level by post‐transcriptional regulation." (PMID 39155453, 2024). "DDIAS may be a potential therapeutic target for tamoxifen-resistant breast cancer since the inhibition of PSPC1 or SCFD2 reduces in vivo tumor development in tamoxifen-resistant breast cancer." (PMID 37121974, 2023). "Finally, we examined the role of SCFD2 in in vivo tumor growth of tamoxifen-resistant breast cancer cells." (PMID 35681031, 2022). "Finally, we demonstrated that siRNA-mediated SCFD2 silencing suppressed in vivo tumor growth of tamoxifen-resistant breast cancer cells, suggesting that SCFD2 can be a promising therapeutic target of tamoxifen-resistant breast cancer." (PMID 35681031, 2022). "In conclusion, the present results suggest that PSPC1 would facilitates hormone-dependent breast cancer proliferation by exhibiting RNA processing of ESR1 and SCFD2, the latter further contributes to anti-apoptotic or proliferative responses by modulating the expression of DDIAS and MYBL1." (PMID 35681031, 2022).
autism (1 paper, 2023). Persistent deficits in social interaction and communication and interaction as well as a markedly restricted repertoire of activity and interest as well as repetitive patterns of behavior. "Interestingly, another report spotlighted SCFD2 as an autism-implicated gene with high-confidence single nucleotide polymorphisms in its 3’UTR miRNA recognition element, potentially affecting its expression." (PMID 38025430, 2023). "Two novel autism genes, TRPC4 and SCFD2, were discovered in two Qatari autism individuals." (PMID 38025430, 2023).
autism spectrum disorder (1 paper, 2023). A spectrum of developmental disorders that includes autism, and Asperger syndrome. "In summary, our study has revealed the involvement of four known genes (DEAF1, CLCN3, KMT2C, and DHX30) as well as two novel genes (TRPC4 and SCFD2) in autism spectrum disorder across six families from Qatar." (PMID 38025430, 2023).
bipolar disorder (1 paper, 2023). A disorder of the brain that causes unusual shifts in mood, energy, activity levels and the ability to carry out day-to-day tasks. "A genome-wide association study identified SCFD2 as one of the susceptibility gene among 15 highlighted genes on chromosome 4 for schizophrenia, bipolar disorder, and major depressive disorder." (PMID 38025430, 2023).
breast tumor (1 paper, 2022). "Moreover, we identified DDIAS and MYBL1 as SCFD2 downstream target genes using microarray analysis, and finally showed that SCFD2 silencing suppressed tamoxifen-resistant breast tumor growth in vivo." (PMID 35681031, 2022).
cataract (1 paper, 2022). Partial or complete opacity of the crystalline lens of one or both eyes that decreases visual acuity and eventually results in blindness. "Other results from GWAS analysis also indicated that several variants within the SCFD2 gene locus achieved genome-wide statistical significance in their association with cataracts in the Australian Shepherd breed of domestic dogs." (PMID 36009466, 2022). "Additionally, there were seven SNPs intersecting the groups containing all the cataract cases and those aged above 60; three of which (rs76840465, rs28433905, and rs60128322) could be mapped to the AGMO, SCFD2, and PROSER3 genes." (PMID 36009466, 2022).
corpus callosum agenesis (1 paper, 2023). "Furthermore, bi-allelic mutations in HS2ST1, another SCFD2 interactor, have been associated with developmental delay, intellectual disability, corpus callosum agenesis, facial dysmorphism, and skeletal and renal anomalies." (PMID 38025430, 2023).
diabetes (1 paper, 2022). "Additionally, the SCFD2 gene has been associated with adiposity and diabetes." (PMID 36009466, 2022).
endometriosis (1 paper, 2018). The growth of functional endometrial tissue in anatomic sites outside the uterine body. "Second, the low-frequency variant rs765333492 (SCFD2, MAF = 0.3%) found only in the Icelandic dataset also shows suggestive association with endometriosis in Iceland (P = 0.018, logistic regression, OR = 1.92)." (PMID 30194396, 2018).
ischemia (1 paper, 2022). A hypoperfusion of the BLOOD through an organ or tissue caused by a PATHOLOGIC CONSTRICTION or obstruction of its BLOOD VESSELS, or an absence of BLOOD CIRCULATION. "In terms of its potential role in ophthalmic diseases, a previous study has found the opposite effect of the Scfd2 gene on STAT1 and miR-493 regulators, which are associated with ischemia, a type of common pathological pathway for neuronal cell degeneration associated with many retinal diseases." (PMID 36009466, 2022).
personality disorder (1 paper, 2022). A diverse category of psychiatric disorders characterized by behavior that deviates markedly from the expectations of the individual's culture; this pattern of deviation is pervasive and inflexible and is stable over time. "The sec1 family domain (SCFD2) gene, identified in the older group, is a protein-coding gene that participates in protein transport and exocytosis and is involved in multiple personality disorders." (PMID 36009466, 2022).
tumor (2 papers, 2021 to 2022). "Our analysis identified several genes with recurrent HBV integration, including TERT, MLL4, ADAM12, PREX2, and SCFD2 in tumor tissues." (PMID 34209079, 2021).
SCFD2 also shares sentences with these, for which no sentence is quoted: cardiomyopathy (1 paper); developmental delay (1); heart failure (1); Intellectual disability (1); major depressive disorder (1); retinal diseases (1); schizophrenia (1).